ZPBP (zona pellucida binding protein)
Description:
Plays a role in acrosome compaction and sperm morphogenesis. Is implicated in sperm-oocyte interaction during fertilization (By similarity).
Synonyms: ZPBP1; SP38; SPGF66
Tractability: Antibody: UniProt places it where antibodies can reach, with high confidence; UniProt predicts a signal peptide or a membrane-spanning region; its Gene Ontology location is reachable by antibodies, with medium confidence.
Gene: Protein-coding gene on chromosome 7 (49,850,421 to 50,121,329, reverse strand). Ensembl gene ENSG00000042813.
Subcellular location: Cytoplasmic vesicle, secretory vesicle, acrosome; Cytoplasmic vesicle, secretory vesicle, acrosome membrane; Secreted
Gene Ontology:
Biological process: acrosome assembly; binding of sperm to zona pellucida
Cellular component: acrosomal vesicle; nucleus; zona pellucida receptor complex; acrosomal membrane; extracellular region
Genetic constraint (gnomAD): Loss-of-function variants: 22 observed, 37.41 expected, observed/expected ratio (o/e) 0.59, 90% interval 0.42 to 0.84. The upper end of that interval is the gene's LOEUF score, 0.84, which puts it in group 3 of 6, group 1 being the genes least tolerant of losing a copy. Missense variants: 357 observed, 393.38 expected, observed/expected ratio (o/e) 0.91, 90% interval 0.83 to 0.99. Synonymous variants: 161 observed, 142.17 expected, observed/expected ratio (o/e) 1.13, 90% interval 1 to 1.29.
Homologues: Orthologues: chimpanzee ZPBP (99% identical), macaque ZPBP (96% identical), pig ZPBP (83% identical), dog ZPBP (81% identical), mouse Zpbp (78% identical), rat Zpbp (78% identical), rabbit ZPBP (72% identical). Paralogues in human: ZPBP2 (33% identical).
Diseases named in the same sentence as ZPBP in open-access papers:
ZPBP is named in the same sentence as 13 diseases in open-access papers, as found by Europe PMC text mining. Sharing a sentence is not in itself a finding about the gene and the disease. The quoted sentences say what the papers report.
Globozoospermia (12 papers, 2015 to 2025). Any structural anomaly of the acrosome resulting in a round sperm head. "Collectively therefore, these data suggest that the aetiology of globozoospermia in GL-11 was a homozygous nonsense mutation in ZPBP." (PMID 31985809, 2020). "Mutations in ZPBP have been described before in patients with sperm head defects, but it remains unclear if these patients suffered from globozoospermia." (PMID 31985809, 2020). "Of interest, ZPBP forms part of the same gene interaction network with known globozoospermia genes SPATA16 and DPY19L2, thus suggesting they are mechanistically linked." (PMID 31985809, 2020). "Our study revealed an important role for mutations in ZPBP and CCDC62 in human globozoospermia as well as five new candidate genes." (PMID 31985809, 2020). "We identified two likely pathogenic homozygous nonsense mutations, which most probably lead to a truncated protein (ZPBP; c.931C > T; p.(Gln311*)) or nonsense-mediated mRNA decay (CCDC62; c.442C > T; p.(Gln148*)), in genes previously known to cause globozoospermia when mutated in mice." (PMID 31985809, 2020).
male infertility (4 papers, 2018 to 2025). The inability of the male to effect fertilization of an ovum after a specified period of unprotected intercourse. "The biggest interaction network contained 31 nodes including several down-regulated proteins associated with sperm-oocyte interaction, e.g. acrosin-binding protein (ACRBP) and zona pellucida-binding protein 1 (ZPBP1), which displayed the complexity of the mechanisms under the male infertility." (PMID 30166971, 2018).
inflammatory bowel disease (1 paper, 2014). A spectrum of small and large bowel inflammatory diseases of unknown etiology. "CDH22 is a cadherin protein associated with colorectal cancer disease, while association of ZPBP with inflammatory bowel disease was shown in a previous genome-wide association study." (PMID 25163507, 2014).
primary biliary cirrhosis (1 paper, 2015). "ZPBP2 encodes a protein paralogue of the zona pellucida binding protein and harbors a missense SNP associated with primary biliary cirrhosis." (PMID 26484354, 2015).
ZPBP also shares sentences with these, for which no sentence is quoted: infertile (5 papers); teratospermia (2); allergic rhinitis (1); asthma (1); Azoospermia (1); infection (1); invasive ductal carcinomas (1); macrozoospermia (1); Obesity (1).